EPB42 (erythrocyte membrane protein band 4.2)
Description:
Component of the ankyrin-1 complex, a multiprotein complex involved in the stability and shape of the erythrocyte membrane.
Synonyms: PA; MGC116735; MGC116737; SPH5
Tractability: Small molecule: a structure with a bound ligand is known. Antibody: its Gene Ontology location is reachable by antibodies, with high confidence; UniProt places it where antibodies can reach, with medium confidence.
Gene: Protein-coding gene on chromosome 15 (43,197,227 to 43,221,018, reverse strand). Ensembl gene ENSG00000166947.
Subcellular location: Cell membrane; Cytoplasm, cytoskeleton
Subcellular location (Human Protein Atlas): Cytosol; Nucleoplasm
Gene Ontology:
Molecular function: protein binding; ATP binding; protein-glutamine gamma-glutamyltransferase activity; structural constituent of cytoskeleton
Biological process: peptide cross-linking; cytoskeleton organization
Cellular component: ankyrin-1 complex; cytoskeleton; plasma membrane; cell periphery; cortical cytoskeleton; membrane
Genetic constraint (gnomAD): Loss-of-function variants: 49 observed, 80.6 expected, observed/expected ratio (o/e) 0.61, 90% interval 0.48 to 0.77. The upper end of that interval is the gene's LOEUF score, 0.77, which puts it in group 3 of 6, group 1 being the genes least tolerant of losing a copy. Missense variants: 727 observed, 909.77 expected, observed/expected ratio (o/e) 0.8, 90% interval 0.75 to 0.85. Synonymous variants: 310 observed, 356.54 expected, observed/expected ratio (o/e) 0.87, 90% interval 0.79 to 0.95.
Homologues: Orthologues: chimpanzee EPB42 (98% identical), macaque EPB42 (93% identical), rabbit EPB42 (83% identical), dog EPB42 (77% identical), pig EPB42 (74% identical), mouse Epb42 (73% identical), rat Epb42 (73% identical), zebrafish tgm5l (28% identical), zebrafish tgm8 (14% identical). Paralogues in human: TGM2 (33% identical), TGM5 (33% identical), TGM7 (32% identical), TGM6 (31% identical), TGM3 (30% identical), TGM4 (27% identical), TGM1 (26% identical), F13A1 (25% identical).
Diseases named in the same sentence as EPB42 in open-access papers:
EPB42 is named in the same sentence as 33 diseases in open-access papers, as found by Europe PMC text mining. Sharing a sentence is not in itself a finding about the gene and the disease. The quoted sentences say what the papers report.
hereditary spherocytosis (18 papers, 2009 to 2026). Hereditary spherocytosis is a congenital hemolytic anemia with a wide clinical spectrum (from symptom-free carriers to severe hemolysis) characterized by anemia, variable jaundice, splenomegaly and cholelithiasis. "EPB42 deficiency causes hereditary spherocytosis, leading to chronic haemolytic anemia with abnormally shaped erythrocytes." (PMID 29143667, 2017). "SPH1 (Spherocytosis, type 1), SPH2 (Spherocytosis, type 2), SPH3 (Spherocytosis, type 3), SPH4 (Spherocytosis, type 4), SPH5 (Spherocytosis, type 5) are caused by ANK1, SPTB, SPTA1, SLC4A1, and EPB42 gene mutations, respectively." (PMID 37795245, 2023). "Particularly interesting for us were five genes associated with clinical phenotypes of hereditary spherocytosis (SPTA1, SPTA, SLC4A1, ANK1, and EPB42)." (PMID 36979763, 2023). "Thirteen variants were identified in five hereditary spherocytosis-related genes (six in ANK1 [SPH1]; four in SPTB [SPH2]; and one in each of SPTA1 [SPH3], SLC4A1 [SPH4], and EPB42 [SPH5])." (PMID 35022413, 2022). "At a correlation cut-off of 0.8, a coexpression subnetwork of 26 GWAS-associated genes was centered on three known Mendelian genes causative for spherocytosis (SLC4A1, EPB42) and congenital anemia (KLF1)." (PMID 32888494, 2020). "Hereditary spherocytosis (HS) is an inherited disorder characterized by anemia, splenomegaly, and spherical-shaped erythrocytes, caused by mutations in erythrocyte membrane Protein Genes (ANK1, SPTB, SLC4A1, SPTA1, and EPB42)." (PMID 33014018, 2020). "The characteristics that EPB42 and SLC4A1 was over expressed in hereditary spherocytosis was consistent with the hematological features of PMF that the presence of large amount of erythrocyte in the peripheral blood cell smear." (PMID 34633991, 2021). "However, genetic testing by NGS showed no mutations in ANK1, EPB42, SLC4A1, SPTA1, or SBTB genes in this and an additional two patients, thus ruling out hereditary spherocytosis in all studied cases." (PMID 35681698, 2022).
anemia (5 papers, 2009 to 2023). A reduction in the number of red blood cells, the amount of hemoglobin, and/or the volume of packed red blood cells. "mRNA relative quantification of red cell membrane protein genes in a Polish patient with α-thalassaemia trait indicated EPB42 as the gene that could also be involved in anaemia pathogenesis." (PMID 19508687, 2009). "In addition, mRNA relative quantification of the red cell membrane protein genes in the Polish patient indicated the EPB42 gene as the one that could also be involved in anaemia pathogenesis." (PMID 19508687, 2009).
gout (2 papers, 2022). A condition characterized by painful swelling of the joints, which is caused by deposition of urate crystals. "A new study characterized plasma eccDNA in gouty arthritis and identified several eccDNA genes such as COL1A1 and EPB42, which were considered to be closely associated with hyperuricemia and gout." (PMID 36256570, 2022). "A total of 256 eccDNA-associated genes were detected as gout unique eccDNA genes, including COL1A1 and EPB42, which potentially contribute to hyperuricemia and gout, and a couple of genes involved in inflammation or immune response." (PMID 35464862, 2022). "COL1A1 and EPB42, which potentially contribute to hyperuricemia and gout, were also revealed by gout eccDNAs." (PMID 35464862, 2022).
thalassemia (2 papers, 2009 to 2024). An inherited blood disorder characterized by a decreased synthesis of one of the polypeptide chains that form hemoglobin. "In our study, we found overexpression of the genes SLC4A1, ANK1, EPB41, EPB42, SPTA1, SPTB, and STOM, all of which are involved in maintaining erythrocyte structure and function, in patients with thalassemia and SCD." (PMID 39519257, 2024).
atherosclerosis (1 paper, 2025). A disease characterized by the build-up of fatty material and calcium deposition in the arterial wall resulting in partial or complete occlusion of the arterial lumen. "Applying MAGEIT to a genome-wide analysis of gene–alcohol interactions on hypertension and seated systolic blood pressure in the Multiethnic Study of Atherosclerosis revealed genes like EIF2AK2, CCNDBP1, and EPB42 influencing blood pressure through alcohol interaction." (PMID 39538414, 2025).
blood disease (1 paper, 2021). A disease that occurs in the blood. "Consequently, our results discussed the connections between the hub genes EPB42, CALR, SLC4A1, MPL and PMF together with other related blood diseases comprehensively." (PMID 34633991, 2021). "Besides, positive staining of EPB42 in erythrocyte and the expression of EPB42 in PBMC also demonstrated a high correlation with blood diseases." (PMID 34633991, 2021).
cerebral amyloid angiopathy (1 paper, 2019). "ANK1 binds to the erythrocyte membrane protein band 4.2 (EPB42, present in this module) to vimentin which is implicated in neuroinflammation and in cerebral amyloid angiopathy, which is one of the major causes of ICH." (PMID 30836997, 2019).
Hypertension (1 paper, 2025). The presence of chronic increased pressure in the systemic arterial system. "While no genes reached genome-wide significance in the hypertension analysis, MAGEIT_RAN yielded the 2 lowest P-values among the 5 methods tested and identified 2 genes, CCNDBP1 and EPB42, located at the cytogenetic region 15q15.2, previously reported to be associated with blood pressure." (PMID 39538414, 2025).
polycythemia (1 paper, 2023). Abnormally high mass or concentration of red blood cells in the blood, either due to an increase in erythropoiesis or a decrease in plasma volume. "Of note, the deficiency or mutation of the genes such as EPB42, SPTB and SPTA1 can cause hereditary polycythemia, 25], which is also an important cause of hemolytic anemia." (PMID 37507679, 2023).
protein deficiency (1 paper, 2023). "Previous research has shown that erythrocyte membrane protein deficiency caused by pathogenic mutations in the ANK1, SLC4A1, SPTA1, SPTB, and EPB42 genes is the molecular pathogenesis of HS." (PMID 36647015, 2023).
tumor (2 papers, 2021 to 2022). "Based on the findings above, this study found EPB42 and SLC4A1 had a strong correlation with PMF, immunofluorescence of EPB42 proved our results in this study, which were detected highly expressed in tumor samples." (PMID 34633991, 2021).
EPB42 also shares sentences with these, for which no sentence is quoted: Spherocytosis (4 papers); breast carcinoma (3); Splenomegaly (2); cardiac hypertrophy (1); colon cancer (1); congenital anemia (1); Congenital hemolytic anemia (1); Elliptocytosis (1); genetic disorder (1); hemochromatosis (1); hemoglobinopathies (1); Hyperbilirubinemia (1); hyperuricemia (1); leukocytosis (1); lung carcinoma (1); malaria (1); nephrolithiasis (1); pancreatic cancer (1); Parkinson’s (1); Sepsis (1); Spherocytosis, type 3 (1); thrombosis (1).